KRT7 (keratin 7)
Diseases named in the same sentence as KRT7 in open-access papers (continued):
Sharing a sentence is not in itself a finding about the gene and the disease.
tumor (continued). "However, two of the three keratins associated with the luminal subtype did show only modest (KRT7) or no expression (KRT20) in the tumor transplants." (PMID 30550540, 2018). "An immunohistochemistry analysis of the tumor in the bile duct and the lymph nodes showed high proliferative activity (Mib-1 < 32%); cells were strongly positive for estrogen receptors (90%) and also positive for progesterone receptors (20%), mammaglobin and cytokeratin-7 (CK-7)." (PMID 25515643, 2014). "Ultimately, we carefully chose LDHA and KRT7 to explore their oncogene role in LUAD, given that they were significantly upregulated in tumor tissues in both mRNA and protein levels, while they were risky genes based on survival analysis." (PMID 41488744, 2026). "ALB+KRT7+ epithelium from advanced ALD had malignant transformation potential and tumour promotion activity." (PMID 39834100, 2025). "We used keratin expression (KRT7, KRT8, and KRT19) to visualize the tumor area and CD68 to mark myeloid cells." (PMID 40917508, 2025). "CDH1-E-Cad, KRT7/15-CK, MKI67-Ki67 are ST-SP pairs with stronger correlation in tumour regions of both samples." (PMID 40735471, 2025). "Expression analyses using TCGA confirmed tumor downregulation of FAM189A2 and tumor−upregulation of KRT7 and B4GALT1." (PMID 41567189, 2025). "Immunohistochemical staining revealed diffuse KRT7, vimentin, PAX8, e-cadherin, SDHA, SDHB and fumarate hydratase expression in tumor cells." (PMID 39980061, 2025). "Immunohistochemistry (IHC) staining for keratin-7 (CK7), a well-established PDAC marker, revealed its expression in tumor material from both patients." (PMID 41141365, 2025). "While in ALB+KRT7+ epithelium from AC samples, in addition to cell proliferation‐related pathways (e.g., MAPK signalling), tumour‐related pathways were significantly enriched, suggesting malignant transformation potential." (PMID 39834100, 2025). "To further confirm the epithelial identity of the EGFR-low expressing cells, we co-stained tumors with epithelial cytokeratin 7 and EGFR and found subpopulations of the tumor expressing the epithelial marker but having low expression of EGFR." (PMID 39747003, 2025). "Although the tumor cells uniformly expressed HMGA2 protein in all cases, cytokeratin 7, S100 protein, and SOX10 displayed either diffuse positivity or highlighted the luminal and abluminal cell populations, respectively." (PMID 40033554, 2025). "Eight genes exhibited greater than 340-fold increases in expression in tumor tissues (CLDN6, KLK7, WNT10A, MYBL2, MAL2, KRT7, PRSS8, EPCAM; Median (Range) of fold increase = 344 (261–7267))." (PMID 41465326, 2025). "In CIN3 versus normal biopsies, the tumour markers CDKN2A and KRT7 had the highest fold-change, while genes related to a favourable immune response, ARG1 and NCAM1, had the lowest." (PMID 39712018, 2024). "Tumor cells (n=38284; 31.2%, n=8; range 22.5-37.2% per PDAC) were annotated into 7 different subtypes, based on the expression of Pan-Ck, cytokeratin 7 (Ck-7), CD44, S100A4, PTX3, CA-IX, CD74." (PMID 39575252, 2024). "Double IHC staining for Keratin 7 and CD34 revealed that Keratin 7-positive tumor cells were accompanied by CD34-positive hepatic sinusoid-like vessels, mimicking the original structure of the hepatic plate." (PMID 38960952, 2024). "Immunohistochemical (IHC) staining of the tumor cells in skin biopsy was positive for carcinoembryonic antigen (CEA), cytokeratin 7 (CK7), and cytokeratin 20 (CK20)." (PMID 39677069, 2024). "In the present work, we found a lower positivity for cytokeratin 7 in CCA cells surrounding and invading the nerves in histological sections from CCA patients, with respect to the tumor mass." (PMID 38474330, 2024). "To substantiate this classification, we examined the expression of hallmark canonical cell markers of cancer epithelial cells (EPCAM, SOX4, KRT7, KRT18, KRT19, KRT8) in C1 (normal epithelial cells) and the other clusters (tumour epithelial cells)." (PMID 38445456, 2024).
tumor (continued). "In conclusion, the current study demonstrates how low expression of the immune marker ARG1 and high expression of the tumour markers CDKN2A and KRT7 correlate with the group of high oncogenic potential HPV and the development of high-grade CIN." (PMID 39712018, 2024). "Two genes related to a favourable immune response, ARG1 and HLA-DQB2, and the tumour markers CDKN2A and KRT7 were selected for validation with qPCR and further analysis." (PMID 39712018, 2024). "An examination of mRNA levels within the TCGA-GTEx cohort demonstrated a notable increase in KLK10, LAMA3, MET, KRT7, and SFTA2, alongside a decrease in MT1X in tumor samples compared to their normal counterparts." (PMID 38893622, 2024). "Immunohistochemically, the tumor was positive for AE1/AE3, cytokeratin 7, and cytokeratin 20, indicating that it had originated from the urothelium." (PMID 38524652, 2024). "We noted a relative upregulation of specific luminal markers, KRT8 and KRT7, as well as distinctive expression of basal-like marker KRT81 in the migratory tumor subtype." (PMID 38892065, 2024). "Compared to other cell subtypes in the tumour microenvironment, the expression of MET, MUC16, and KRT7 was higher in pancreatic malignant cells." (PMID 37815881, 2023). "KRT7 has been previously reported for its potential use in detection of micrometastasis in GBC and our study confirmed high positivity rate in primary tumor (gallbladder) from LN metastatic GBC." (PMID 37142981, 2023). "In the present case, IHC examination of the tumor revealed that vimentin was positively stained, P63, KRT14, S-100 was focally positive, Ki-67(80%), while KRT5/6, KRT7, GFAP, calponin, SMA, KRT-PAN, SOX10, mammaglobin was negative." (PMID 37705036, 2023). "Immunohistochemical staining showed the tumour cells were diffusely positive for cytokeratin 20 (CK20) and caudal-related homeobox transcription factor 2 (CDX2) while cytokeratin 7 (CK7), Wilms tumour 1 (WT1) and tumour protein 63 (p63) were all negative." (PMID 37032350, 2023). "By immunohistochemistry, tumour cells were neuron-specific enolase (NSE), chromogranin, cytokeratin 7 (CK7) and pan-CK positive." (PMID 36923225, 2023). "In this report, nearly all tumor cells were positive for GATA-3, KRT7, EMA, E-Cadherin, Ksp-Cadherin, 34βE12, and AMACR in varying intensities, focally positive for CD10 and Vimentin, while negative for CD117, TFE3, RCC, and CAIX." (PMID 37143937, 2023). "Previously, we confirmed the presence of tumor cells in all biopsy samples of PDAC tumors and control tissues by cytokeratin 7 staining and histological analyses." (PMID 37894871, 2023). "The detection of cytokeratin 7 (CK7) and cytokeratin 20 (CK20) also contributes to tumor identification." (PMID 36966290, 2023). "The epithelial marker cytokeratin 7 (CK7) was highly expressed in all eight UTUC organoid lines and their source tumor tissues." (PMID 34914855, 2022). "N8 is a neighborhood that contains tumor cells (cytokeratin AE1/AE3 and cytokeratin 7 positive), and high presence of fibronectin." (PMID 35217454, 2022). "Keratin 7 (KRT7), a member of the keratin family, is abnormally expressed in a variety of tumor tissues and has been widely accepted as a prognostic marker for GC." (PMID 35923703, 2022). "Immunohistochemical studies showed positive staining of tumor cells for thyroid transcription factor-1 (TTF-1), napsin A, and Cytokeratin 7 (CK7)." (PMID 36329437, 2022). "In this case, the clear tumor cells showed positivity of MUC-1, cytokeratin 7, and cytokeratin 19, and showed negativity of vimentin and neuroendocrine markers, which indicate pancreatic clear cell carcinoma with ductal phenotype." (PMID 36140448, 2022).
tumor (continued). "Immunohistochemistry (IHC) examination showed that the tumor cells were positive for thyroid transcription factor 1 (TTF-1) and cytokeratin 7 (CK-7)." (PMID 33975638, 2021). "The tumor markers CDKN2A and KRT7 were the most upregulated genes with fold changes 10.7 and 4.8, respectively, while markers for proliferation (MELK, CDK1, MKI67, CCNB2, BUB1, FOXM1, CDKN3) had fold changes spanning from 2.0–2.7." (PMID 35008799, 2021). "Co-immunofluorescence using antibodies directed against LYVE1 and cytokeratin 7, an antigen expressed in ES2 cells, revealed that the‬‏ metastasizing cells originated from the transplanted ES2 tumor cells (arrow)." (PMID 32132179, 2020). "The results of immunostaining with the cell block sample showed that cytokeratin 7 (CK7) and CK20 stained positive for periodic acid–Schiff (PAS), and a mucus-producing tumor was suspected." (PMID 32660614, 2020). "Immunohistochemical analysis showed the tumor tested positive for Cytokeratin 20 (CK20) and Cytokeratin 7 (CK7) that are distributed in epithelia and their neoplasms." (PMID 32832071, 2019). "Cytokeratin 7 (CK7, normal pancreatic ductal marker), CA19-9 (tumor marker), E-cadherin and trypsin (normal pancreatic acinar cell marker) were localized in adherent PK-1 cells and spheres, but not in adherent PANC-1 cells and spheres." (PMID 31350453, 2019). "Immunohistochemical studies confirmed the tumor cells to be immunoreactive with cytokeratin AE1/3, cytokeratin 5/6, cytokeratin 7, p63, and SOX10." (PMID 29651355, 2018). "A great number of tumour cells positive for thyroid transcription factor-1 (TTF-1) and cytokeratin 7 (CK 7) were confirmed by pathological haematoxylin-eosin (HE) staining examination of hydrothorax, combined with immunohistochemical staining." (PMID 30029601, 2018). "The differentially expressed genes in triphasic tumours relative to blastemal tumours included genes published as potential UB/CD markers: MUC1, PKHD1, KRT7, CDH1, and LIF." (PMID 29040332, 2017). "Known epithelial HGSOC markers such as MSLN, PAX8 and KRT7 were higher in the FTEC isolates, HGSOC tumours and group I cell lines compared with groups II and III cell lines (including IOSEs)." (PMID 27561551, 2016). "Next, immunohistochemical (IHC) staining was performed using cytokeratin 7 (CK7), cytokeratin 20 (CK20), and thyroid transcription factor-1 (TTF-1), in order to clarify the origin of the tumor." (PMID 27714647, 2016). "TCGA-A tumours showed higher expression of most group I/FTEC epithelial proteins such as KRT7, MSLN, CDH6, ASS1 and EPCAM, while TCGA-B tumours had higher expression of the group III/IOSE mesenchymal proteins ITGA5, HMOX1, SMTN and GJA1 (refs 7, 34)." (PMID 27561551, 2016). "The tumour cells show immunoreactivity to a range of keratins including AE1/AE3, keratin 7, and neuroendocrine markers such as chromogranin and synaptophysin." (PMID 27429819, 2016). "HPCs/biliary markers including cytokeratin 7 (K7), cytokeratin 19 (K19), Epithelial cell adhesion molecule(EpCAM) and OV6 were stained in the HCC tumor tissues." (PMID 26311117, 2015). "The tumor tissues were further confirmed by immunohistochemical assessments, which showed that thyroid transcription factor 1 (TTF-1 or NKX2–1) and Cytokeratin 7 (CK7) were all significant positive." (PMID 25474437, 2014). "The tumor was diagnosed as invading the visceral pleura and immunohistochemical staining showed caudal-type homeobox transcription factor 2 (CDX-2)(+), mucin-1(+), cytokeratin 7 (CK7)(+) and thyroid transcription factor-1 (TTF-1)(−) in the tumor cells." (PMID 24348839, 2014).
tumor (continued). "Immunohistochemical (IHC) staining test results showed that the tumor cells were positive for pancytokeratin (AE1/AE3), cytokeratin 7 (CK-7), thyroid transcription factor 1 (TTF-1) and carcinoembryonic antigen (CEA)." (PMID 24330633, 2013). "The tumor subtypes reflected by the patient-derived ex vivo cultures were validated by qPCR analysis of keratinization (CNFN, CRNN), basal (KRT5, KRT6), and luminal markers (KRT7, GATA3)." (PMID 41387887, 2025). "The immunohistochemical analysis revealed that the tumor cells were positively labeled with cluster of differentiation 117 protein (CD117), cytokeratin 7 (CK7), and epithelial membrane antigen and negatively labeled with vimentin and cluster of differentiation 10 protein (CD10)." (PMID 40438847, 2025). "Immunohistochemical results showed that the tumor cells positively expressed epithelial membrane antigen (EMA), thyroid transcription factor 1 (TTF1), NapsinA (epithelial cells) and cytokeratin 7 (epithelial cells), while negatively expressed chromogranin A (CgA) and synaptophysin (Syn)." (PMID 40061895, 2025). "The tumor was histologically composed of oncocytic cells that expressed KRT7, vimentin, SDHA, SDHB and fumarate hydratase, but not KIT, GATA3 and alpha-methylacyl-CoA racemase." (PMID 39980061, 2025). "The tumor closely resembled FATPWO both morphologically and immunophenotypically, exhibiting loss of PAX8 and cytokeratin 7 expression, with no identifiable recurrent molecular alterations." (PMID 40959354, 2025). "As depicted, lower MIOX expression was not prominently existed within the core region of tumor (identified by KRT7) but in tumor-adjacent tissue." (PMID 40341358, 2025). "Cytokeratin 7 and CK18 can be considered immunophenotypes for identifying ENA tumour cells." (PMID 40144068, 2025). "IHC analysis revealed expression of E-cadherin, cytokeratin 7 (CK7), and CD117 in tumor cells." (PMID 41416307, 2025). "Recent findings also suggest the expression of cytokeratin 7 (CK7) as a marker of a subset of cells within the TZ, particularly at the SCJ, which may be especially prone to HPV-mediated neoplasia." (PMID 40733555, 2025). "Notably, we observed increased infiltration levels of Tregs, a pivotal immunosuppressive CD4+T cell that promote tumour progression, in high‐ALB+KRT7+ EPCs group." (PMID 39834100, 2025). "The immunohistochemistry results revealed that the tumor cells expressed vimentin and β-catenin, but not cytokeratin 7 (CK7) or chromogranin; therefore, the diagnosis of SPT was confirmed, which had been completely excised with clear margins." (PMID 40625471, 2025). "Pancytokeratin (Pan-CK), cytokeratin 7 (CK7), cytokeratin 18 (CK18), olfactory marker protein (OMP) and Kiel 67 were examined in ENA tumours to clarify the immunohistochemical characteristics of ENA, analyse the tumour origin and screen for suitable antibodies for ENA tumour cell identification." (PMID 40144068, 2025). "The tumour elements are negative for evidence of cytokeratin 7, cytokeratin 20, and oestrogen receptors." (PMID 39582714, 2024). "In the CD335 ESMA CAR-treated tumor core and border, a more pronounced cytoskeletal structure characterized by higher cytokeratin 7 (CK7) and SMA expression compared to the outer tumor region could be observed." (PMID 38203786, 2024). "Tumor cells were positive for cytokeratin 7 (CK7) and GATA3 protein; there was negative staining for cytokeratin 20 (CK20) and mammaglobin." (PMID 38993623, 2024). "The immunohistochemical stains revealed tumor cells of the myometrial nodule to be positive for keratin 20 (CK 20) and negative for keratin 7 (CK 7) and estrogen receptor." (PMID 39803152, 2024).
tumor (continued). "Through assay for transposase-accessible chromatin using sequencing (ATAC-seq), we detected increased chromatin openness of squamous markers (TP63, KRT5, KRT6A and KRT14) and reduced chromatin accessibility of adenomatous markers (KRT7 and MLPH) in the DR tumor cells." (PMID 39687207, 2024). "F. nucleatum was thoroughly correlated with increased tumor invasion and lymph node or distant metastases, promoting metastasis by regulating signaling molecules, including IL-8, C-X-C motif chemokine ligand 1 (CXCL1), and keratin 7 (KRT7)." (PMID 39201711, 2024). "A smaller but still relevant number of tumor cells displayed consistent cytokeratin 7 immunoreactivity (data not shown)." (PMID 39415286, 2024). "The liver metastases and PDX tumor histology slides were negative for AR, PSA, PSAP and ERG protein expression; the tumor strongly expressed KRT7 and focally 34βE12." (PMID 38907236, 2024). "Tumor cells of the two cases showed strong immunoreactivity for AE1/AE3, calretinin, cytokeratin 7 (CK7), podoplanin (D2-40), and weak reactivity for Wilm’s tumor gene-1 (WT1), but were negative to chromogranin A (CgA), cluster of differentiation 34 (CD34), and synaptophysin (Syn)." (PMID 39429478, 2024). "On immunostaining, the tumour cells showed strong expression of calretinin, inhibin, vimentin, WT-1 and oestrogen receptor (ER) and were negative for cytokeratin 7 (CK7), and epithelial membrane antigen (EMA)." (PMID 38376618, 2024). "A next-generation sequencing transcriptomic immune profile analysis applied to 28 persistent CIN3 lesions and 14 normal biopsies identified four genes, the immune markers ARG1 and HLA-DQB2 and the tumour markers CDKN2A and KRT7, as possible markers for differentiating between CIN3 and normal tissue." (PMID 39712018, 2024). "As the tumour cells consistently expressed cytokeratin 7 and PAX8 in absence of cytokeratin 20, carcinoembryonic antigen (CEA) and pancytokeratine, we diagnosed endometrial carcinoma metastatic to the skin in all three locations." (PMID 37013123, 2023). "Tumor cells can be divided into 4 different subtypes, including basaloid cells (KRT5, KRT14), myoepithelial cells (ACTA2, MYL), cycling cells (MKI67, TOP2A) and duct-like cells (KRT7, KRT19)." (PMID 35860547, 2022). "Immunohistochemistry revealed that the tumor cells were positive for cytokeratin 7 but negative for cytokeratin 20 and S100 proteins." (PMID 35622762, 2022). "Epithelial makers (KRT18, KRT19, KRT17, KRT7, and CLDN4) were also highly expressed, indicating that M2 may be derived from transdifferentiation of epithelial cells in the tumor." (PMID 35265520, 2022). "Tumor cells with GATA3 or GRHL2 positive nuclei also contain the pRCC marker cytokeratin 7 (CK7) in the cytoplasm, without any traces of AQP1." (PMID 35013217, 2022). "The tumor cells were negative for cytokeratin 7 (CK-7), cytokeratin 20 (CK-20), thyroid transcription factor 1 (TTF-1), napsin A, prostate specific antigen (PSA), and prostate specific acid phosphatase (PSAP) staining." (PMID 35193475, 2022). "In addition, KRTs and notably KRT7, KRT18 and KRT19, are widely used to detect circulating tumor cells in the blood or detached tumor cells in ascites." (PMID 34070214, 2021). "Tumor cells were cytokeratin 7 negative but cytokeratin 20, CDX2, and carcinoembryonic antigen (CEA) positive." (PMID 34514560, 2021). "Soluble protein fragments of keratins, including KRT7, KRT8, KRT18 and KRT19, can be detected in the circulation of cancer patients and are used to monitor disease progression and patient prognostic in certain tumour types." (PMID 34070214, 2021). "Similarly, regions with strong HA-tag expression in the PDAC tumor graft also expressed less KRT19 and KRT7 and substantially higher levels of mesenchymal markers such as N-CAD (pound sign)." (PMID 34680288, 2021). "Immunohistochemically, the tumor was positive for carbonic anhydrase 9 (CA9) but negative for cytokeratin 7 (CK7), suggestive of metastatic RCC." (PMID 32347406, 2020).